FLT3 (fms related receptor tyrosine kinase 3)
Diseases named in the same sentence as FLT3 in open-access papers (continued):
Sharing a sentence is not in itself a finding about the gene and the disease.
acute myeloid leukemia (continued). "Over the past decade, treatment strategies for acute myeloid leukemia (AML) have undergone substantial transformation, with a growing emphasis on combining targeted agents, such as BCL-2, FLT3, and IDH inhibitors, with conventional chemotherapy to enhance patient outcomes." (PMID 41294812, 2025). "In acute myeloid leukemia (AML), OC may enhance responses to FLT3 inhibitors such as gilteritinib by suppressing STAT3-mediated survival signals in FLT3-ITD mutant cells." (PMID 40564985, 2025). "EGFR, KIT, and FLT3 mutants are well known as major oncogenic drivers of lung adenocarcinoma (LAD), gastrointestinal stromal tumor (GIST)/mast cell leukemia (MCL), and acute myeloid leukemia (AML), respectively." (PMID 38679330, 2024). "We select six representative genes from CancerMine, which include three most frequently reported genes in the context of acute myeloid leukemia (AML), KMT2A, FLT3, and MLLT3, as well as three genes that are least reported in this specific cancer, namely ZFP36L2, ZIC2, and ZNF582." (PMID 38431735, 2024). "Consequently, this could be considered a great help to combat resistance mechanisms of acute myeloid leukemia cells as the inhibition of both FLT3 and Mnk2 resulted in increasing the apoptotic cell death of MV4-11 cells compared to inhibition of FLT3 or Mnk2 individually." (PMID 37438819, 2023). "The in-frame internal tandem duplication (ITD) of the FLT3 gene is an important negative prognostic factor in acute myeloid leukemia (AML)." (PMID 37190162, 2023). "Moreover, VPS34-IN1 inhibits autophagy in acute myeloid leukemia (AML) cells via impairing vesicular trafficking and mTORC1 signaling in connection with STAT5 phosphorylation, downstream of FLT3-ITD signaling." (PMID 36034776, 2022). "Although mutations in FLT3 have been well-documented in cases of acute myeloid leukemia (AML) and other hematological malignancies, there is currently no substantial evidence demonstrating that FLT3 plays a role in the tumorigenesis of CRC." (PMID 32087735, 2020). "Midostaurin resulted from a drug discovery effort to improve the protein kinase C inhibitory activity of Staurosporine and targets constitutively activated mutant FMS-like tyrosine kinase-3 (FLT3), which is expressed in a subpopulation of patients with acute myeloid leukemia (AML)." (PMID 31491907, 2019). "Quizartinib is an oral, once-daily, highly potent and selective second-generation, type II FMS-like tyrosine kinase 3 (FLT3) inhibitor, approved for the treatment of newly diagnosed and relapsed/refractory (R/R) FLT3-internal tandem duplication (ITD)-positive acute myeloid leukemia (AML)." (PMID 41746494, 2026). "HHT in combination with heat shock protein 90 (HSP90) inhibitors synergistically reduces FLT3 expression and inhibits downstream signaling pathways, including STAT5, AKT, ERK, and 4E-BP1, demonstrating efficacy in treating FLT3-ITD-positive acute myeloid leukemia (AML)." (PMID 39949739, 2025). "Several studies have characterized the nature of FLT3 expression in human and murine cells and identified its importance in early hematopoiesis (CD34+cells), and also shown that FLT3 expression can be high in hematologic malignancies such as acute myeloid leukemia (AML)." (PMID 39200232, 2024). "Indeed, various oncogenes, such as BCR-ABL1 or FLT3-ITD, were reported to support high levels of basal autophagy sustaining cell proliferation and leukemogenesis in chronic myeloid leukemia (CML) or in acute myeloid leukemia (AML), respectively." (PMID 37423955, 2023). "In addition, core binding factor acute myeloid leukemia (CBF-AML), nucleophosmin 1 (NPM1) and fms related receptor tyrosine kinase 3 (FLT3) in risk stratification have no impact on the expression of BRD4, PD-L1 and PD-1." (PMID 33658927, 2020).
acute myeloid leukemia (continued). "We have recently reported that N-CoR actively represses Flt3, a key factor of hematopoietic stem cells (HSC) self-renewal and growth, and that de-repression of Flt3 by the misfolded N-CoR plays an important role in the pathogenesis of promyelocytic and monocytic acute myeloid leukemia (AML)." (PMID 26500885, 2015). "DNMT3A, FLT3, and NPM1 mutations are among the most common genomic alterations in de novo acute myeloid leukemia (AML) and play a key role in the pathogenesis and evolution of the disease, particularly in the absence of AML-associated recurrent cytogenetic abnormalities." (PMID 25281355, 2014).
leukemia (683 papers, 2006 to 2026). A malignant (clonal) hematologic disorder, involving hematopoietic stem cells and characterized by the presence of primitive or atypical myeloid or lymphoid cells in the bone marrow and the blood. "The drug combination also showed greater inhibition of cell proliferation and increased apoptosis in NPM1 mutated and KMT2A‐rearranged leukemia models with FLT3 mutations." (PMID 39887730, 2026). "HHT can be administered in conjunction with other therapeutic agents to treat leukemia associated with FLT3-ITD mutations by modulating cell signaling pathways, inducing apoptosis, and affecting stem cell properties." (PMID 39949739, 2025). "In leukemia, particularly with FLT3-ITD mutations, YAP1 levels are reduced, and restoring its expression can delay tumor progression." (PMID 41479777, 2025). "To further immunophenotypically define these preLSCs, we assessed the expression of hematopoiesis-regulating receptors, such as Il-7r, Notch1, Kit, and Flt3, which have been implicated in leukemia development." (PMID 39849166, 2025). "This indicates that the FLT3-ITD mutation directly contributes to leukemia cell resistance to initial induction chemotherapy." (PMID 41294667, 2025). "Recent studies have demonstrated the metabolic alterations associated with FLT3 mutation in leukemia cells." (PMID 40263296, 2025). "Overall, our data show that preLSCs expressing high levels of Flt3 display increased long-term self-renewal capacity and proliferation associated with progressive expansion during leukemia development." (PMID 39849166, 2025). "HHT and gilteritinib can upregulate Ubiquitin Conjugating Enzyme E2 L6 (UBE2L6) together, promoting the degradation of Mcl-1 through the ubiquitin-proteasome pathway, and bring an effective drug target for FLT3-ITD mutated leukemia." (PMID 39949739, 2025). "The Flt3 molecule is well-studied in the context of hematology, particularly for its role in leukemia, where constitutive phosphorylation due to mutations drives oncogenesis." (PMID 40076904, 2025). "Despite the challenges of balancing antileukemic efficacy with preservation of normal cellular metabolism, the identification of specific metabolic vulnerabilities of FLT3-mutated leukemia cells opens new avenues for targeted therapeutic strategies." (PMID 41003134, 2025). "A GO analysis of affected genes listed the mitogen‐activated protein kinase pathway, consistent with the previous findings of intracellular signalling pathways potentiated by the FLT3 genetic mutations in leukemia cells." (PMID 40181449, 2025). "One such example is the receptor tyrosine kinase Flt3, which is critical for blood cell development and is implicated in the pathogenesis of leukemia when dysregulated." (PMID 40076904, 2025). "Examples abound, including the impact of KIT mutations and secondary genetic lesions in core-binding factor leukemia, as well as the influence of age on FLT3-ITD mutated leukemia." (PMID 38571944, 2024). "This study demonstrated that the USP14/UCHL5 inhibitors b-AP15 and AUR effectively inhibited the K48-mediated deubiquitination of ubiquitin bound to FLT3 in leukemia cells with FLT3-ITD mutations." (PMID 39408703, 2024). "In ALL, genes in the relevant signaling pathways were downregulated in the mutation group, whereas in AML, they were upregulated, highlighting the differing roles of FLT3 mutations in the development of these leukemias." (PMID 39273530, 2024). "Quizartinib’s primary mechanism involves the inhibition of FLT3 tyrosine kinase activity, thus blocking FLT3 mutation-induced signaling pathways that are essential for leukemia cell proliferation and survival." (PMID 38643300, 2024). "Together, our data suggests that FLT3-ITD+ leukemia-associated cDCs polarize CD4+ T cells into Th17 subsets, a population that has been shown to be negatively associated with survival in solid tumor contexts." (PMID 38495876, 2024).
leukemia (continued). "In our study, CBF leukemia was more common in the adolescent cohort (38%), while FLT3-ITD mutations, typically higher in adolescents, were reported in 7.5% of patients." (PMID 38539480, 2024). "These regulators cause leukemia pathogenesis and affect disease diagnosis and prognosis when they co-occur with FLT3-ITD mutation." (PMID 38696033, 2024). "High levels of FLT3 have been associated with phosphorylation and ligand-independent activation in leukaemia, which makes patients with FLT3 overexpression susceptible for targeted therapy." (PMID 38049555, 2024). "Another study identified a leukemia-associated immunophenotype (LAIP) of CD25+/CD34+/CD99+/CD123+ that is strictly associated with FLT3 ITD in AML with NPM1 mutation and a normal karyotype." (PMID 39594810, 2024). "Specifically, leukemia-promoting FMS-like tyrosine kinase 3 (FLT3) mutations modulate nuclear transcription and upregulate SUCLG1 expression to reduce succinyl-CoA and POLRMT succinylation, resulting in enhanced mitobiogenesis." (PMID 38649537, 2024). "6% in MOLM14-cMyc-siRNA vs. MOLM14-cMyc-scramble cells, respectively, p < 0.05), implying that c-Myc suppression has a role in CG-806-induced inhibition of cell growth through G1 phase arrest in FLT3-mutated leukemia cells." (PMID 36865133, 2023). "Treatment with extremely low doses (nanomolar to sub-nanomolar) of CG-806 for 72 h profoundly inhibited cell growth via apoptosis induction in both human and murine leukemia cell lines harboring either FLT3-ITD mutations or FLT3-ITD+TKD point mutations." (PMID 36865133, 2023). "Given the established role of these mutations in AML, FLT3 inhibitors became a standard of care among leukemia therapies." (PMID 37239765, 2023). "Collectively, these results demonstrated that sitravatinib exerted potent and specific anti-leukemia effects on AML cells harboring FLT3-ITD mutation." (PMID 36691065, 2023). "To evaluate the anti-leukemia potency of CG-806, we compared the cytotoxic effects of the drug with other currently approved/available FLT3 and multi-kinase inhibitors in FLT3-mutated and FLT3-WT AML cell lines and patient samples." (PMID 36865133, 2023). "Immunoblotting of MV4-11 and MOLM13 cells showed that sitravatinib-mediated anti-leukemia effects were associated with the dephosphorylation of FLT3 and its downstream molecules STAT5, AKT and ERK." (PMID 36691065, 2023). "The cooperative mechanisms of multiple mutations (e.g., combined DNMT3A, NPM1, and FLT3 mutations) also need to be investigated to better understand the mechanisms of progression to overt leukemia." (PMID 38116120, 2023). "This will be very interesting and helpful for understanding the role of both FLT3 and CEBPΑ aberrations in leukaemia development using the clinical outcomes of AML patients carrying FLT3 and CEBPΑdm co-occurrence mutations treated with FLT3i therapies." (PMID 37019911, 2023). "These signaling cascade proteins are highly expressed and constitutively activated in FLT3-mutated leukemia cells." (PMID 36865133, 2023). "In line with our in vitro results, CG-806 had robust anti-leukemia activity in a murine xenograft model of leukemia created using the aggressive FLT3-ITD-mutated Ba/F3 cells, and in a PDX AML model as well." (PMID 36865133, 2023). "Biologically, mice transgenic for the fusion gene PML::RARA manifested a pre-leukaemic state of deranged myeloid maturation, with an APL-like leukaemia only developing if collaborating mutations such as internal tandem duplication of FLT3 were present." (PMID 36765318, 2023). "Revumenib treatment blocks leukemic engraftment and prevents leukemia-associated death of immunodeficient mice transplanted with NUP98::NSD1 FLT3-ITD-positive patient-derived AML cells." (PMID 37520776, 2023). "It has been discovered that melatonin caused FLT3/ITD human leukaemia cells to undergo apoptosis via transferring cytochrome c from the mitochondria into the cytosol." (PMID 37645444, 2023).
leukemia (continued). "A newer generation FLT3i, crenolanib is still under development and showed impressive anti-leukemia effects against resistant AML harboring FLT3 TKD mutations." (PMID 36865133, 2023). "On the other hand, FOXO3 acts as a tumor suppressor, and phosphorylation of FOXO3 by FLT3-ITD results in inactivation of FOXO3-mediated apoptosis in leukemia with FLT3-ITD mutation." (PMID 38007419, 2023). "In a mouse retroviral model of AML, MIF produced by a FLT3-mutated subclone was observed to favor the expansion of leukemia-initiating cells." (PMID 35115654, 2022). "Taken together, these in vitro results suggest that NOX4 is relevant under conditions of leukemia cell competition in FLT3-mutated cell lines." (PMID 35348887, 2022). "Individual risk stratification by molecular profiling of leukemia samples and availability of many effective agents for molecular subtypes, e.g., FLT3 inhibitors or IDH1/2 inhibitors, allow the first steps towards personalized AML therapy." (PMID 35406464, 2022). "FLT3-ITD mutations are an alarming gene defect found commonly in AML patients associated with high cases of leukemia and low survival rates." (PMID 35323440, 2022). "SYK also plays a key role in AML in terms of phosphorylating signal transducer and activator of transcription 5 (STAT5) and cooperating with FLT3-ITD in maintaining leukemia, and is also associated with an unfavorable prognosis." (PMID 35216478, 2022). "Our novel approach is the assembly of an antibody-based siRNA nanocarrier to induce specific RNAi against mutated DNMT3A and FLT3 in leukemia." (PMID 36457063, 2022). "Remissions associated with FLT3 inhibition are usually short-lived, commonly due to the persistence of therapy-refractory leukemia stem cells (LSCs), despite clearance of the bulk of leukemia progenitor cells (LPCs)." (PMID 35681619, 2022). "Combined inhibition of menin-MLL and FLT3 represents a promising new therapeutic strategy for patients with FLT3mut leukemia with NPM1mut or MLL mutation." (PMID 36077850, 2022). "CDDD11-8 reduced the proliferation of leukemia cell lines and was particularly effective against those harboring FLT3-ITD mutation." (PMID 35267421, 2022). "Further studies revealed that reduced DOCK2 expression decreased Rac1, ERK and STAT5 activity in leukemia cells bearing FLT3-ITD mutations." (PMID 36250020, 2022). "Leukemia with FLT3-ITD mutations accounts for a rare form of AML with high rates of relapse and drug resistance." (PMID 36481875, 2022). "Inhibition of autophagy enhanced the anti-leukemia effect of sorafenib in leukemia cell lines and primary blasts with FLT3-ITD + D835Y mutation, which opens a window for overcoming FLT3 inhibitor resistance in AML with acquired D835 mutation." (PMID 35794565, 2022). "As with the chemotherapy cohort, AZA+Pembro treatment was associated with downregulation of leukemia-associated genes (FLT3, CD34)." (PMID 36099049, 2022). "For example, it has conclusively been shown that circMYBL2, derived from AML-related gene MYBL2, exerts a cancerogenic role in leukemia harboring FLT3-ITD mutation." (PMID 36058922, 2022). "Inhibition of FLT3 function or mutation of FLT3 gene prevents the binding of ATP to FLT3 kinase domain, thus promoting leukemia cell proliferation and anti-apoptosis process to additional drug treatment." (PMID 36481875, 2022). "Breaking a single allele from the Fms-related tyrosine kinase 3 (FLT3) gene using a site-specific TALEN lead to the creation of isogenic leukemia cell clones." (PMID 36358785, 2022). "Two randomized studies evaluated the role of sorafenib in the prophylaxis post-HSCT in FLT3-mutated leukemia." (PMID 35011994, 2022). "Due to the genetic heterogeneity of AML, the coexistence of FLT3 mutated and FLT3 wildtype (wt) leukemia cells is frequent." (PMID 35406464, 2022).